ALDOC (aldolase, fructose-bisphosphate C)
Diseases named in the same sentence as ALDOC in open-access papers (continued):
Sharing a sentence is not in itself a finding about the gene and the disease.
colorectal cancer (6 papers, 2021 to 2025). A primary or metastatic malignant neoplasm that affects the colon or rectum. "Herein, the expression of ALDOC in colorectal cancer tissues and its correlation with tumor pathological features and patient survival were detected and analyzed, respectively." (PMID 40518543, 2025). "In conclusion, this study identified ALDOC/PGK1 axis as a key promotor of colorectal cancer development through inducing glycolysis." (PMID 40518543, 2025). "Among the aldolase family, ALDOC is currently relatively poorly studied, and the aim of this study is to explore its function in colorectal cancer cell phenotype as well as glycolysis regulation." (PMID 40518543, 2025). "Collectively, these findings demonstrate that ALDOC knockdown attenuates tumor growth in vivo, suggesting a potential therapeutic strategy for colorectal cancer." (PMID 40518543, 2025). "By constructing a colorectal cancer cell model that interferes with ALDOC expression, ALDOC-induced regulation of colorectal cancer cell phenotype as well as glycolysis was studied." (PMID 40518543, 2025). "Unsurprisingly, PGK1 also functions in concert with ALDOC to regulate glycolysis-related parameters as well as malignant phenotypes of colorectal cancer cells." (PMID 40518543, 2025). "Accordingly, ALDOC also showed a significant promoting effect on the proliferation and migration phenotypes of colorectal cancer cells in vitro, and on tumor growth in vivo." (PMID 40518543, 2025). "Our work, on the other hand, more clearly showed that ALDOC has a significant regulatory effect on glucose uptake, lactate production, and ATP production of colorectal cancer cells, indicative of its direct regulatory effect on colorectal cancer glycolysis." (PMID 40518543, 2025). "In summary, ALDOC may be a key molecular target to block glycolysis as well as tumor progression of colorectal cancer." (PMID 40518543, 2025). "The inhibition of ALDOC reduced lactate production in colorectal cancer cells." (PMID 38739943, 2024).
schizophrenia (4 papers, 2009 to 2020). A major psychotic disorder characterized by abnormalities in the perception or expression of reality. "Another investigation using samples of post mortem hippocampus of patients with schizophrenia found that glycolysis- and gluconeogenesis-associated proteins were altered, as seen by decreased levels of ALDOC and increased ENO1." (PMID 30890939, 2019). "Proteomics analysis of post mortem brains of patients with schizophrenia showed alterations in the levels of energy metabolism-associated proteins, such as aldolase C (ALDOC), enolase 2 (ENO2), and glyceraldehyde-3-phosphate dehydrogenase (GAPDH)." (PMID 30890939, 2019). "In this review, in schizophrenia, ALDOC is the most frequently abnormally-expressed protein identified in proteomic studies of the brain, where its expression is predominantly astrocytic, but some studies of schizophrenia find elevated levels and others find depressed levels." (PMID 26909022, 2016). "A study of the protein changes in ACC in schizophrenia, MDD and bipolar disorder found that cytoskeletal and mitochondrial proteins are the most prominently altered in all of these disorders, but only 2 identified proteins (SRI, ALDOC) were found with changed levels in both schizophrenia and MDD." (PMID 26909022, 2016).
gastric cancer (3 papers, 2023 to 2025). A primary or metastatic malignant neoplasm involving the stomach. "ALDOC demonstrates significant overexpression in gastric cancer (GC) and colorectal cancer (CRC), where it directly promotes tumor proliferation, invasion, and metastasis through glycolytic reprogramming – a hallmark of the Warburg effect." (PMID 40313939, 2025). "Previous research revealed a positive association of ALDOB expression with the survival of patients with gastric cancer and ALDOC as a target for positive regulation by the retinoblastoma (RB) tumor suppressor protein." (PMID 37834179, 2023). "Furthermore, ALDOC is significantly correlated with immune infiltration in gastric cancer by influencing macrophage differentiation." (PMID 38238671, 2024).
lung carcinoma (3 papers, 2019 to 2023). "Here, we sought to investigate the functional roles and underlying mechanism of ALDOC in lung cancer." (PMID 37724906, 2023). "However, the specific roles of ALDOC in lung cancer and the underlying mechanisms governing its function in cancer remain poorly understood." (PMID 37724906, 2023). "To uncover the mediators of ALDOC’s effects on lung cancer development, we performed a gene expression analysis using the genechip primeview human patharrayTM in A549 cells after shALDOC and shCtrl infection." (PMID 37724906, 2023). "Expression patterns of ALDOC in lung cancer tissues and para-carcinoma tissues revealed in immunohistochemistry analysis." (PMID 37724906, 2023). "Overall, our findings highlight the potential of ALDOC as a promising therapeutic target for lung cancer." (PMID 37724906, 2023). "Relationship between ALDOC expression with lymph node metastasis, lymphatic metastasis and stage in patients with lung cancer." (PMID 37724906, 2023). "Relationship between ALDOC expression and tumor characteristics in patients with lung cancer." (PMID 37724906, 2023). "Silencing UBE2N achieved the same effects on lung cancer cells as knocking down ALDOC." (PMID 37724906, 2023). "Thus, we concluded that ALDOC regulates the proliferation, migration, and apoptosis of lung cancer cells via targeting UBE2N." (PMID 37724906, 2023). "Furthermore, silencing UBE2N achieved the same effects on lung cancer cells as knocking down ALDOC." (PMID 37724906, 2023).
astrocytoma (2 papers, 2019 to 2024). "Further classification revealed that ALDOC was generally less frequently expressed in GBM than in oligodendrogliomas, astrocytomas, and LGGs." (PMID 38741139, 2024).
bipolar disorder (2 papers, 2016 to 2021). A disorder of the brain that causes unusual shifts in mood, energy, activity levels and the ability to carry out day-to-day tasks. "In fact, the two most referenced biomarkers of SCZ, namely Fructose-bisphosphate aldolase C (ALDOC) and Glial fibrillary acidic protein (GFAP), are also altered in major depression and bipolar disorder." (PMID 33668817, 2021).
brain injuries (2 papers, 2021). "Fructose-bisphosphate aldolase C (ALDOC) is a glycolytic enzyme found to be upregulated after spinal or brain injuries." (PMID 34572572, 2021). "ALDOC is highly expressed in some tumor cells, and cerebral spinal fluid (CSF) ALDOC is also expressed markedly higher after traumatic brain injury (TBI)." (PMID 34243818, 2021).
brain tumors (2 papers, 2024). "Similar to the metabolomes of brain tumors, FIA10 cells likely rely on glycolysis for energy production rather than mitochondrial activity or oxidative phosphorylation, reminiscent of the Warburg effect, as they have highly up-regulated brain specific aldolase C (ALDOC) RNA and protein expression." (PMID 38215076, 2024).
colon cancer (2 papers, 2023 to 2025). "In line with these knowledge, we also represented that ALDOC is also a therapeutic target associated with glycolysis in colon cancer." (PMID 35778964, 2023). "Particularly, we demonstrated that BRD9 mediates the enrichment of H3K27ac at ENO2 and ALDOC gene loci, thereby enhancing the glycolytic activities of colon cancer cells." (PMID 35778964, 2023).
cutaneous melanoma (2 papers, 2021 to 2025). A primary melanoma arising from atypical melanocytes in the skin. "We investigated whether the MGCM‐mediated upregulation of ALDOC expression is restricted to MBMs being preconditioned by microglia‐derived signals or if matching cutaneous melanoma would also express upregulated levels of ALDOC." (PMID 33274599, 2021).
medulloblastoma (2 papers, 2024). A malignant, invasive embryonal neoplasm arising from the cerebellum. "However, two proteins, ALDOC and ITIH4, were significantly elevated in medulloblastoma patients within the Reichl cohort." (PMID 38350915, 2024).
mood disorder (2 papers, 2013 to 2021). A cognitive disorder a disturbance in which the person's mood is hypothesized to be the main underlying feature. "ALDOC is a brain-specific glycolytic enzyme that, in agreement with previous reports on mood disorders, was found to be upregulated in diseased subjects." (PMID 34576123, 2021). "However, previous reports showed that protein expression level of ALDOC was increased in the frontal cortex of patients, including those with mood disorder." (PMID 23408933, 2013).
Obesity (2 papers, 2021 to 2024). Accumulation of substantial excess body fat. "Interestingly, the current study did enrich a fructose metabolic gene, ALDOC, which has been implicated in obesity and type II diabetes." (PMID 34349727, 2021).
oral squamous cell carcinoma (2 papers, 2023 to 2024). "A study has shown a significant correlation between high ALDOC expression and longer survival duration of patients with advanced oral squamous cell carcinoma." (PMID 37397364, 2023).
ovarian carcinoma (2 papers, 2020 to 2023). A malignant neoplasm originating from the surface ovarian epithelium. "The silencing of lncRNA-NRCP could reduce the levels of glucose-6-phosphate isomerase ALDOA and ALDOC. lncRNA-NRCP via STAT1 could promote glycolysis in ovarian cancer cells." (PMID 33123468, 2020).
brain cancer (1 paper, 2024). A primary or metastatic malignant neoplasm affecting the brain. "Therefore, the ALDOC expression level is closely associated with the occurrence of brain cancer." (PMID 38741139, 2024). "This study examined alterations in ALDOC expression in different subtypes of brain cancer." (PMID 38741139, 2024).
chronic myeloid leukemia (1 paper, 2017). "In the chronic myeloid leukemia model (K562Dox) the following 4 DEPs were found to be involved in the GSH metabolism pathway (G6PD, PRDX2, IDH1 and 6PGD), 3 DEPs in the PPP pathway (G6PD, ALDOC and 6PGD) and 2 DEPs in the glycolysis pathway (ALDOC and PKM2)." (PMID 28303926, 2017).
diabetes (1 paper, 2023). "For instance, TXNDC5’s interactions with NENF, PPP1R2, ALDOC, LDH, or PGD may help explain its relevance in diabetes." (PMID 38138960, 2023).
fatty liver disease (1 paper, 2025). A reversible condition wherein large vacuoles of triglyceride fat accumulate in liver cells via the process of steatosis. "The interactions between saroglitazar and ferulic acid with different enzymes and metabolites involved in metabolic dysfunction-associated fatty liver disease (MASLD), such as SORD, HK1, HK2, MgATP, KHK, HK3, ALDOB, ALDOC, and fructose-1-phosphate (F1P)." (PMID 40130107, 2025).
Insulin resistance (1 paper, 2019). Increased resistance towards insulin, that is, diminished effectiveness of insulin in reducing blood glucose levels. "Serine hydroxymethyltransferase 1 (SHMT1), ALDOC, SDSL, ASS1, and IDH3A are novel biomarkers for the development of insulin resistance." (PMID 30678306, 2019).
intrahepatic cholangiocarcinoma (1 paper, 2025). A carcinoma that arises from the intrahepatic bile duct epithelium in any site of the intrahepatic biliary tree. "Based on the training and validation cohorts of intrahepatic cholangiocarcinoma (ICA) bulk transcriptomes, seven metabolic enzymes were confirmed to be overexpressed in cases with poor prognosis: FH, MAT2B, PLOD2, PLOD1, PDE6D, ALDOC, and NT5DC3." (PMID 40034261, 2025). "Univariate logit binomial analysis, with the outcome being the proliferative subclass status of intrahepatic cholangiocarcinoma, confirmed the significance of the probes for seven enzymes: FH, MAT2B, PLOD2, PLOD1, PDE6D, ALDOC, and NT5DC3." (PMID 40034261, 2025).
lymph node metastasis (1 paper, 2023). "ALDOC expression was associated with lymph node metastasis, lymphatic metastasis and pathological stage." (PMID 37724906, 2023). "Notably, ALDOC expression showed a significant positive correlation with lymph node metastasis, lymphatic metastasis, and pathological stage." (PMID 37724906, 2023).
Parkinson disease (1 paper, 2019). A progressive degenerative disorder of the central nervous system characterized by loss of dopamine producing neurons in the substantia nigra and the presence of Lewy bodies in the substantia nigra and locus coeruleus. "A recent study proved that the expression of ALDOC in Parkinson’s disease was often accompanied by some atypical clinical symptoms, but rarely associated with disease progression." (PMID 31450822, 2019).
proliferative diabetic retinopathy (1 paper, 2023). Advanced retinopathy due to diabetes mellitus characterized by the formation of new vessels in the retina. "Our study highlighted ALDOC, a member of the class I fructose-bisphosphate aldolase gene family, as a key protein associated specifically with proliferative diabetic retinopathy (PDR)." (PMID 38274229, 2023).
prostate carcinoma (1 paper, 2025). A carcinoma that arises from epithelial cells of the prostate gland. "In addition, their experiments demonstrated that ADPGK could promote glycolysis in prostate cancer cells through activation of the ALDOC-AMPK pathway." (PMID 41035662, 2025).
renal carcinoma (1 paper, 2017). A carcinoma arising from the epithelium of the renal parenchyma or the renal pelvis. "Consistent with the data that FILNC1 regulates the expression of glucose metabolism genes, computational analyses revealed a negative correlation between FILNC1 and ALDOC, or PDK1 in renal cancer." (PMID 28978906, 2017).
tumor (38 papers, 2011 to 2025). "Among the two cell types, H460-derived tumor spheroids seem more affected by the single knock down of ALDOC, which alone causes the significant down regulation of ENO2 and the significant accumulation of intracellular glucose amount." (PMID 36945054, 2023). "Furthermore, previous studies have implicated BMAL1 and ALDOC in metabolic reprogramming and tumor progression, particularly under hypoxic conditions." (PMID 40535800, 2025). "Our results suggest that loss of ALDOC function in GBM promotes tumor cell invasion and migration." (PMID 38741139, 2024). "To summarize, the analysis of biological functions and disease pathways in cells with ALDOC overexpression clearly indicated the ALDOC‐mediated induction of genes associated with tumor progression in YDFR.CB3 cells and antitumor progression properties in DP.CB2 cells." (PMID 33274599, 2021). "The analysis of biological functions and disease pathways in the ALDOC overexpressing variants clearly indicated that ALDOC induced the expression of tumor progression promoting genes in the first variant and antitumor progression properties in the second variant." (PMID 33274599, 2021). "Our analysis revealed a significant upregulation of ALDOC expression in tumor tissues compared to normal tissues." (PMID 40518543, 2025). "Its impact is highly context-dependent, often dictated by the tumor microenvironment: certain conditions enable ALDOC to support tumor glycolysis and growth, whereas in other contexts ALDOC activity suppresses tumor progression." (PMID 40520908, 2025). "In this study, our results suggest that the HIF-1α/BMAL1/ALDOC pathway functions to enhance anaerobic glycolysis in tumor cells, thus reducing the sensitivity of CRC to L-OHP." (PMID 40535800, 2025). "In order to investigate the in vivo effects of ALDOC knockdown on CRC tumor growth, we established an animal model by injecting RKO cells with or without ALDOC knockdown into the right flank of nude mice." (PMID 40518543, 2025). "Our findings are consistent with those of other researchers, indicating that interference with ALDOC expression can inhibit glycolysis and consequently suppress tumor growth." (PMID 40313939, 2025). "Immunohistochemical (IHC) analysis of the tumor tissues further confirmed the downregulation of Ki67 expression, a marker of cell proliferation, in tumors derived from the shALDOC group, validating the efficacy of ALDOC knockdown in the tumor tissues." (PMID 40518543, 2025). "Immunohistochemical (IHC) staining of locally collected patient-derived tissues corroborated these findings, demonstrating elevated ALDOC expression in tumor tissues, particularly in advanced stages." (PMID 40518543, 2025). "HIF-1α and ALDOC were important in enhancing the malignant degree of tumor and reducing the sensitivity of L-OHP chemotherapy." (PMID 40535800, 2025). "Using median for dividing high/low ALDOC expression groups, survival analysis further demonstrated that patients with high ALDOC expression in tumor tissues exhibited relatively shorter progression-free survival and overall survival." (PMID 40518543, 2025). "The experimental results illustrated that hypoxic cells treated by L-OHP showed decreased glycolysis of tumor cells after ALDOC knockdown." (PMID 40535800, 2025). "Classified into three groups (ALDOA, ALDOB, and ALDOC), ALDOA has been implicated in promoting tumor growth and metastasis in various cancers." (PMID 39765841, 2024). "Previous studies have investigated the tumor suppressor function of aldolase C (ALDOC), a glycolytic enzyme in GBM." (PMID 38741139, 2024). "Consistent with our expectations, forced expression of ALDOC led to increased tumor volume and weight." (PMID 37724906, 2023). "The aberrant expression of aldolase family members has been demonstrated to promote tumor progression; ALDOC is upregulated in various cancers and acts as a regulator of Wnt signaling." (PMID 36845730, 2023).